G6PD (glucose-6-phosphate dehydrogenase)
Diseases named in the same sentence as G6PD in open-access papers (continued):
Sharing a sentence is not in itself a finding about the gene and the disease.
lung carcinoma (continued). "To substantiate our results by 6-AN treatment in lung cancer cells, we checked the expression of PPP-related genes such as G6PD, HPGD, TKT, and TALDO1 in these cells 48 h after 6-AN treatment." (PMID 34827081, 2021). "Recently, it was reported that a paralog of G6PD, hexose-6-phosphate dehydrogenase (H6PD), that is present in the endoplasmic reticulum of cells, affects PPP flux in breast and lung cancer in a similar manner to G6PD." (PMID 33946927, 2021). "Studying H6PD biological role in breast and lung cancer, here we show that gene silencing of this reticular enzyme decreases cell content of PPP intermediates and d-ribose, to a similar extent as G6PD silencing." (PMID 33335166, 2020). "In lung cancer, YTHDF2 directly binds to the m6A modification site (3′-UTR) of glucose 6-phosphate dehydrogenase (6PGD) to promote the translation of 6-PGD and the proliferation of lung cancer cells." (PMID 33552994, 2020). "In summary, this study uncovers a new function of HPD in promoting PPP and tumor growth of lung cancer cells, and demonstrates that this previous unrecognized function of HPD is mediated through the G6PD–PPP flux axis." (PMID 31285420, 2019). "Overexpression and upregulation of two enzymes of the oxidative phase, i.e., glucose-6-phosphate 1-dehydrogenase (G6PD) and 6-phosphogluconate dehydrogenase (PGD), contributes to increased production of NADPH and ribose-5-phosphate in lung cancer." (PMID 31803611, 2019). "In this study, we demonstrated that the HPD–glucose-6-Phosphate Dehydrogenase (G6PD) axis enhanced the oxidative pentose phosphate pathway (PPP) flux and facilitated lung cancer growth." (PMID 31285420, 2019). "Glucose-6-phosphate dehydrogenase (G6PD) is the rate-limiting enzyme of the PPP, and hypoxia triggers its O-GlcNAcylation at Ser-84 in human lung cancers, leading to G6PD activation and metabolic flux into the PPP to produce intermediates of nucleotide and lipid biosynthesis in cancer cells." (PMID 39178944, 2024). "Besides, activity of glucose-6-phosphate dehydrogenase (G6PD), the rate-limiting enzyme of the pentose phosphate pathway (PPP), was reported to be activated in response to hypoxia in human lung cancers." (PMID 33990217, 2021). "Expression of PPP enzymes such as G6P dehydrogenase (G6PD), 6-phosphogluconate dehydrogenase (PGD), and transketolase (TKT) was directly regulated by NRF2 in lung cancer cells, and NRF2 overexpression redirected cell metabolism to PPP-mediated purine nucleotide synthesis." (PMID 31078780, 2019). "Although our GEMM findings highlight the role of G6PD in promoting KL, not KP, tumorigenesis, a deeper investigation is warranted to comprehend the implications of this discovery for the growth and treatment of KL or KP tumors in lung cancer patients." (PMID 38997257, 2024). "However, G6PD reportedly undergoes modifications such as phosphorylation at Y112 and Y428 in HCT116 cells, acetylation at K403 in leukaemia cells and glycosylation at S84 in lung cancer cells." (PMID 37491277, 2023). "These analyses demonstrated that mRNA expression of G6PD, glutaminase (GLS), hydroxy-prostaglandin dehydrogenase 15-(NAD) [HPGD], TKT, TALDO1, ribulose-5-phosphate-3-epimerase (RPE), and transketolase-like-1 (TKTL1) were more abundant in lung cancer patient samples." (PMID 34827081, 2021). "Collectively, these results suggest that G6PD glycosylation may play a role in lung cancer initiation, but not progression of the disease." (PMID 26399441, 2015). "Hence, the present study aimed to determine whether the pharmacological blockade of glucose 6-phosphate dehydrogenase (G6PD), the primary and rate-limiting enzyme involved in PPP, using 6-aminonicotinamide (6-AN), could induce antiproliferative activity in two lung cancer cell lines." (PMID 34827081, 2021). "In lung cancer patients with KRAS WT, except for MTHFD1, the expression levels of G6PD, IDH1, and ME1 were not correlated with the patient survival time." (PMID 38997257, 2024).
Hyperbilirubinemia (49 papers, 2011 to 2026). An increased amount of bilirubin in the blood. "Among the G6PD-deficient infants, early-onset jaundice occurred in 17.2%, phototherapy was required in 36.0%, and 16.5% were admitted for hyperbilirubinemia management." (PMID 42042691, 2026). "The underlying mechanisms of physiologic neonatal hyperbilirubinemia seem to be aggravated and intensified in G6PD-deficient neonates." (PMID 40564624, 2025). "Diagnostic evaluation of a neonate with pathological hyperbilirubinemia includes maternal and neonatal AΒO and Rh-status, direct antibody test, complete blood count, reticulocyte count, peripheral blood smear, and G6PD testing." (PMID 40564624, 2025). "It has also been reported that co-inheritance of a uridine diphosphate glucuronosyltransferase 1A1 (UGT1A1) gene variant is an additional risk factor for neonatal hyperbilirubinemia in G6PD-deficient male neonates." (PMID 38480787, 2024). "As observed elsewhere, G6PD-deficient newborns had the highest risk of developing hyperbilirubinemia owing to a mechanism only partially explained by increased hemolysis." (PMID 37669757, 2023). "G6PD-deficient newborns are less likely to respond well to conventional treatment methods for hyperbilirubinemia and are at greater risk for permanent brain damage or death during infancy." (PMID 38132231, 2023). "In Chaozhou of eastern Guangdong province, among 882 neonates with hyperbilirubinemia, 74 cases (8.39%) were G6PD-deficient, and in Fujian province, the prevalence of G6PD deficiency among neonates with hyperbilirubinemia was 7%." (PMID 37492600, 2023). "The prevalence of G6PD-deficient in severe hyperbilirubinemia (TSB ≥ 342 μmol/L) and mild-medium jaundice (TSB < 342 μmol/L) was 30% (15 out of 50, 11 males, 4 females) and 18.18% (70 out of 385, 49 males, 11 females), respectively." (PMID 37492600, 2023). "Further studies should investigate the differences and to distinguish between the G6PD variants, their combinations, and co-inheritance with other genes for bilirubin-related metabolism in favism and severe hyperbilirubinemia." (PMID 35685917, 2022). "Of interest, in our previously published study, neonates with the G6PD Gaohe (c.95A > G) variant had severe hyperbilirubinemia and were five times more likely to require phototherapy during the first week." (PMID 35685917, 2022). "Altogether, an elevated bilirubin level in the blood as well as ineffective clearance from the liver causes the build-up of serum bilirubin leading to neonatal hyperbilirubinemia, which occurs more frequently and severely in G6PD-deficient infants." (PMID 35685917, 2022). "Hyperbilirubinemia is the common symptom seen in G6PD, and if left untreated, can cause severe motor and cognitive impairments." (PMID 35466197, 2022). "The Biosensor is a suitable tool in this resource-constrained setting to identify newborns with abnormal G6PD phenotypes at increased risk of neonatal hyperbilirubinaemia." (PMID 36523222, 2022). "It was also reported that co-inheritance of a uridine diphosphate glucuronosyltransferase 1A1 (UGT1A1) gene variant is an added risk factor for neonatal hyperbilirubinemia in G6PD-deficient male neonates." (PMID 35685917, 2022). "TATA mutation of UGT1A1 promoter coupled with G6PD deficiency was indicated as an important factor for neonatal hyperbilirubinemia in Nigeria." (PMID 34895177, 2021). "Seventy four cases (8.36%, 67 males and 7 females) were G6PD deficient in 882 neonates with hyperbilirubinemia. cases (2.05%, 10 males and 2 females) were G6PD deficient among 585 controls." (PMID 34895177, 2021). "In 74 G6PD-deficient cases with hyperbilirubinemia, there were 6 cases of homozygous mutation of c.211G > A, 27 cases of heterozygous mutation, and 41 cases of wild type." (PMID 34895177, 2021). "The G6PD genotypes of 74 hyperbilirubinemia cases with G6PD-deficient were determined by flow-through hybridization." (PMID 34895177, 2021).
Hyperbilirubinemia (continued). "Clinical manifestations of our G6PD-deficient children were classified as 91 individuals (89.2%) with neonatal hyperbilirubinemia (66 males and 25 females) and 11 individuals (10.8%) with acute hemolytic anemia (7 males and 4 females)." (PMID 33628497, 2021). "A previous study in a referral center reported that of 4,906 patients hospitalized for hyperbilirubinemia, 55 were G6PD deficient." (PMID 29474382, 2018). "This was the most likely trigger of haemolysis in 50% of G6PD deficient newborns that presented with severe hyperbilirubinaemia in our study." (PMID 29935542, 2018). "A cross‐sectional study conducted in 2006 at Cipto Mangunkusumo National Referral Hospital Jakarta, investigated 36 full‐term G6PD deficient neonates with hyperbilirubinemia." (PMID 28361095, 2017). "In this study, G6PD enzyme deficiency in neonatal pathologic hyperbilirubinemia in Yazd was evaluated." (PMID 24575273, 2013). "A literature review indicated a paucity of data regarding association of G6PD c.563C > T with the clinical course of neonatal hyperbilirubinemia." (PMID 22906047, 2012). "Additional risk factors for hyperbilirubinemia were observed in eight or 23% G6PD deficient infants; including pre-term (n = 4), ABO or Rh incompatibility (n = 3), and preterm with sepsis (n = 1)." (PMID 22906047, 2012). "Comparison of G6PD c.563 > T group (n = 21) with G6PD normal infants (n = 184) showed that these G6PD variant infants were at higher risk for early and moderate hyperbilirubinemia." (PMID 22906047, 2012). "We recognize this limitation to our program as G6PD-deficient females may develop hyperbilirubinemia as deficient homozygotes or as hemizygotes with unequal Lyonization." (PMID 41007072, 2025). "In our cohort of infants with hyperbilirubinemia, the hemoglobin levels in the G6PD-deficient group were significantly lower than those in the normal G6PD group (P < 0.001), and slightly higher than those in the ABO hemolysis group (134.33 ± 24.18 g/L) (P = 0.014)." (PMID 37492600, 2023). "G6PD genotypes distribution in 65 cases of G6PD deficient infants with hyperbilirubinemia." (PMID 37492600, 2023). "Similarly, the variants G6PD Kaiping (c.1388G > A) and G6PD Canton (c.1376G > T), common among those of Chinese ancestry are reportedly more at risk for severe hyperbilirubinemia." (PMID 35685917, 2022). "Moreover, the peak bilirubinin of the G6PD-deficient group of hyperbilirubinemia neonates was 334.43 ± 79.27 μmol/L, higher than that of the normal G6PD group of hyperbilirubinemia neonates (300.30 ± 68.62 μmol/L)." (PMID 34895177, 2021). "Another important assay that is used to identify the risk factors for neonatal hyperbilirubinemia is glucose-6-phosphate dehydrogenase (G6PD) enzyme activity, which identifies the relatively common deficiency of this enzyme (1 in 8 African American males are affected)." (PMID 31906315, 2020). "We screened for G6PD gene variants in infants with pathologic jaundice in the Wuhan area and found that gene variants were detected in 28.1% of infants, which is comparable to 31.5% detection rate reported by Yazd in Neonatal Pathologic Hyperbilirubinemia." (PMID 32680472, 2020). "The increased risk of hyperbilirubinemia in G6PD-deficient neonates might have been further aggravated by an early exposure to naphthalene-containing mothballs used routinely by almost half of the local population." (PMID 29895274, 2018). "The Child Health Epidemiology Reference Group (CHERG) modeling study estimates that 78% of cases of extreme hyperbilirubinemia are attributable to Rh disease, 6% to glucose 6-phosphate dehydrogenase deficiency (G6PD), 2% to moderate/late preterm birth, and 15% to other causes." (PMID 29474382, 2018).
Hyperbilirubinemia (continued). "This study aims to identify risk factors and the neurodevelopmental impact of neonatal hyperbilirubinemia in a limited-resource setting among a refugee and migrant population residing along the Thai-Myanmar border, an area with a high prevalence of glucose-6-phosphate dehydrogenase-deficiency." (PMID 28109243, 2017). "The findings suggest that a high incidence of neonatal hyperbilirubinemia in Taiwan may be derived from high prevalence of gene variants in G6PD, nt211 in UGT1A1, and HO-1 promoter GT-repeat." (PMID 27557546, 2016). "Other studies have also shown that bilirubin levels of G6PD deficient neonates may spontaneously spike even in the absence of environmental triggers, shedding some light on the spontaneity of hyperbilirubinemia in G6PD deficient neonates." (PMID 25610485, 2014). "Additionally, at the time of recognition of hyperbilirubinemia, the serum total bilirubin was significantly higher for this variant in contrast to G6PD normal infants of the same age group." (PMID 22906047, 2012). "Because it is associated with very low enzyme activity, we hypothesized that the neonates inheriting this variant would exhibit severe hyperbilirubinemia requiring more aggressive management compared to icteric infants having normal G6PD activity." (PMID 22906047, 2012). "However, few reports (primarily from Chinese populations) have investigated the relationship between G6PD variants and the severity of neonatal hyperbilirubinemia, while others focused only on identification of G6PD variants in icteric infants." (PMID 22906047, 2012). "However, the clinical impact of specific G6PD gene variants on hyperbilirubinemia severity remains unclear." (PMID 41769530, 2026). "G6PD-deficient infants with severe hyperbilirubinemia often are not well correlated with hemolysis according to hematological indices, though researches using carboxyhemoglobin or end tidal CO have shown that hemolysis plays a major role in the pathophysiology of severe hyperbilirubinemia." (PMID 38480787, 2024). "Additionally, multivariate logistic regression analysis identified that the mutant genotype of rs4148323 in the UGT1A1 gene, ABO incompatibility, G6PD deficiency, and SS genotype at rs1805173 locus of the HO-1 gene were genetic risk factors of neonatal hyperbilirubinemia." (PMID 30298137, 2018). "In contrast, jaundice involving severe hyperbilirubinemia can occur in infants with underlying conditions such as ABO incompatibility, Rhesus incompatibility, or glucose-6-phosphate dehydrogenase (G6PD) deficiency." (PMID 40498757, 2025). "Neonatal hyperbilirubinemia, which is often linked to UGT1A1 and G6PD variants, is highly prevalent in China, affecting approximately 34.4% of full-term neonates and is generally considered treatable." (PMID 40421383, 2025). "Glucose-6-phosphate dehydrogenase (G6PD) deficiency and polymorphism in uridine diphosphate glucuronosyl transferase 1A1 (UGT1A1) were associated with significant neonatal hyperbilirubinemia (NHB) and increased risk for kernicterus." (PMID 37508669, 2023). "Hyperbilirubinemia with predominantly free bilirubin is also noted in G6PD hemolytic anemias with collapsed haptoglobin." (PMID 36845240, 2022). "It is timely that a WHO working committee is regrouped to review the G6PD classification, stratifying of risks, diagnosis, therapy, and prevention, focusing on neonatal hyperbilirubinemia." (PMID 35685917, 2022). "We proposed that the neonates with hyperbilirubinemia should be screened for G6PD activity actively and timely." (PMID 34895177, 2021). "The present study was aimed at evaluating the time to onset of hyperbilirubinemia and the postnatal bilirubin trajectory in infants having G6PD c.563C > T." (PMID 22906047, 2012). "Kaplan in 2001 studied 52 infants with G6PD c.563C > T and observed hyperbilirubinemia in 16 (30.8%) neonates, in contrast to 10 (6%) controls." (PMID 22906047, 2012).
Hyperbilirubinemia (continued). "Among 20 neonates with hyperbilirubinaemia, G6PD Viangchan was also found at the highest frequency (60%), followed by G6PD Canton (10%), G6PD Mahidol, G6PD Union, and G6PD Kaiping (5% each)." (PMID 22171972, 2011). "Not all G6PD-deficient patients had severe hyperbilirubinemia requiring ET during their hospital stay." (PMID 36147809, 2022). "Furthermore, integration of G6PD test results across multiple clinical indications, such as hyperbilirubinaemia in neonates, will likely require improved genetic counseling, health systems strengthening, and improved record keeping and data management." (PMID 32766454, 2020). "Here we present a complete mutational and polymorphism analysis of G6PD and its activity in newborns with and without hyperbilirubinemia in Indonesian Deutromalay population." (PMID 31862010, 2019). "The prevalence of G6PD mutations in neonates with and without hyperbilirubinemia were 6.8% (95% CI: 2.3–11.5%) and 6.9% (95% CI: 2.3–11.6%), respectively." (PMID 31862010, 2019). "The severe hyperbilirubinemia in neonates of our study justifies more prolonged hospitalization and more frequent use of exchange transfusion for them in comparison with neonates who had normal activity of G6PD." (PMID 24575273, 2013). "A few reports from Chinese population illustrated G6PD variants in neonatal hyperbilirubinemia but those reports did not demonstrate G6PD c.563C > T and therefore their results were not comparable to our work." (PMID 22906047, 2012). "This study underscores the correlation of G6PD c.563C > T with neonatal hyperbilirubinemia." (PMID 22906047, 2012). "The lack of knowledge on G6PD is a major concern as an estimated 15–26% of the Ghanaian population have G6PD defect and there is established evidence of its association with hyperbilirubinaemia when infants with the defect are exposed to oxidants such as naphthalene balls." (PMID 35239710, 2022). "Due to the limited number of cases studied, the relationship between bilirubin level and neonatal hyperbilirubinemia could not be determined in other types of G6PD mutation." (PMID 34895177, 2021). "Neonatal hyperbilirubinemia is quite common in Indonesia; however, it is not yet known whether G6PD genetic variants (polymorphisms and mutations) and deficiency are the risk factors for NH in the Indonesian population." (PMID 31862010, 2019). "This study demonstrated that hyperbilirubinemia may occur spontaneously even without exogenous factors for G6PD deficient neonates." (PMID 25610485, 2014). "In addition, G6PD normal infants requiring exchange transfusion (n = 28) had comorbid like septicemia and prematurity (25/28 or 89%) which would have contributed towards significant hyperbilirubinemia and hence a need for exchange transfusion." (PMID 22906047, 2012). "Yet another enigma is that, often in G6PD-deficient infants with severe hyperbilirubinemia, there may be no overt evidence of hemolysis in the peripheral blood film nor marked reticulocytosis, characteristic of most conditions causing hemolytic anemia and jaundice." (PMID 35685917, 2022). "This study aimed to analyze the G6PD genetic variations and its activity in neonates with and without hyperbilirubinemia in the Deutromalay Indonesian population." (PMID 31862010, 2019).